LEP (leptin)
Diseases named in the same sentence as LEP in open-access papers (continued):
Sharing a sentence is not in itself a finding about the gene and the disease.
Obesity (continued). "Increased leptin levels were pronounced in relationship with obesity and are associated with higher cancer risk." (PMID 40783771, 2025). "Altered adiponectin and leptin concentrations are associated with increased inflammation in obesity." (PMID 40034592, 2025). "Leptin regulates immune cell function changes associated with obesity via mTOR regulation, which regulates protein synthesis, ribosome biogenesis, and autophagy, modulating proinflammatory immune cell functions." (PMID 40696355, 2025). "A melanocortin 4 receptor (MC4R) agonist, setmelanotide (Set), is used to treat obesity caused by abnormal melanocortin and leptin signaling." (PMID 40232848, 2025). "In IL-23-treated adipocytes, the upregulated genes included typical obesity markers such as Lep, which encodes leptin." (PMID 40860129, 2025). "In the pathophysiological association between obesity and asthma, adipose tissue eosinophils, IL-4, and leptin form a key regulatory network via the immune-metabolic axis." (PMID 41244254, 2025). "Dysregulated HPA function also impacts leptin and insulin resistance pathways, further impairing energy balance and exacerbating cognitive deficits in obesity and air pollution exposure-linked conditions." (PMID 41515969, 2025). "The cross-sectional design limits the ability to establish causal relationships between leptin levels, obesity, and glycemic status." (PMID 40630340, 2025). "Massive obesity with preserved insulin sensitivity is also observed in leptin-deficient (ob/ob) male and female mice overexpressing the mitochondrial membrane protein, mitoNEET." (PMID 37961647, 2025). "The SH2B1 gene, recently identified as a candidate for non-syndromic monogenic obesity, encodes an intracellular adaptor protein involved in signaling pathways downstream of receptor tyrosine kinases, including leptin, BDNF, and insulin receptors." (PMID 40077044, 2025). "At the same time, exercise stimulates the secretion of leptin, insulin and other hormones and mediates the uptake of blood sugar and blood lipids by skeletal muscle, thus reducing the risk of obesity." (PMID 41048303, 2025). "Obesity has been linked to genetic predispositions that alter insulin and leptin signaling, contributing to insulin resistance and leading to behavioral disorders, including aggression and social isolation." (PMID 40367227, 2025). "The association of these SNVs in the leptin gene with anthropometric variables and obesity has been reported in several studies in children, including samples of different ages, with discordant results among studies." (PMID 41465332, 2025). "In the present work, HFD-induced obesity-associated nephropathy caused hyperleptinemia, and Cinnamaldehyde significantly reversed the elevated leptin level to preserve kidney function." (PMID 40703753, 2025). "Obesity is associated with dysregulation in circulating adipokines, i.e., high leptin and low adiponectin levels." (PMID 40095937, 2025). "In the context of obesity, leptin becomes dysregulated due to diminished response of body cells to leptin stimulus resulting in leptin resistance and associated overeating." (PMID 40759955, 2025). "Our findings confirm that BC is an obesity-associated cancer with a relevant role potentially played by Leptin." (PMID 41409302, 2025). "Obesity, on the other hand, is associated with elevated leptin levels, which can promote chronic low-grade inflammation by activating both innate and adaptive immune cells." (PMID 40095902, 2025). "Association between obesity and adipokines is well established and includes anti-inflammatory adiponectin and proinflammatory leptin." (PMID 40565591, 2025). "Elevated leptin levels, often observed in obesity, are associated with a pro-inflammatory state, as leptin promotes the activation and survival of various immune cells, including neutrophils and T lymphocytes." (PMID 40076537, 2025).
Obesity (continued). "Obesity-associated TNBC is characterized by elevated circulating leptin levels, which have been linked to metabolic status and tumor aggressiveness." (PMID 41463012, 2025). "Adipose tissue also produces a variety of adipokines and proinflammatory cytokines linked to obesity-associated male infertility, including leptin, adiponectin, resistin, ghrelin, TNF-alpha, IL-1β and IL-6." (PMID 40140188, 2025). "Leptin/leptin receptor signaling can promote obesity-associated asthma by inducing M1 macrophage polarization, leading to nonallergic asthma characterized by excessive neutrophil infiltration in the airways." (PMID 40319236, 2025). "Several studies have reported that hypothalamic ER stress is closely associated with obesity and leptin resistance." (PMID 40427263, 2025). "Leptin is among the adipokines contributing to the chronic inflammatory state associated with obesity, which predisposes individuals not only to type 2 diabetes, metabolic syndrome, and cardiovascular disease, but also to autoimmune and allergic disorders." (PMID 40095902, 2025). "Obesity is associated with chronically high leptin levels but impaired hypothalamic and hippocampal leptin receptor signaling." (PMID 41516046, 2025). "Obesity disrupts adipokine equilibrium, primarily through an increase in leptin levels, which is associated with IR and maternal hyperglycemia, and a reduction in adiponectin, leading to hypoadiponectinemia frequently seen in GDM." (PMID 39962434, 2025). "The genetic leptin-deficient ob/ob mice and are widely used as animal models to study obesity and related metabolic disorders." (PMID 41213922, 2025). "Literature indicates that obesity is associated with leptin resistance, a condition in which the hormone loses its ability to inhibit appetite and increase energy expenditure." (PMID 40862455, 2025). "In particular, the direct association between CAMKK1 and leptin was observed as attenuated in individuals with obesity, while the direct association between CAMKK1 and blood glucose or TNFα was strengthened in patients with T2DM." (PMID 40965347, 2025). "The in vivo activity of FGF21-164 was evaluated in leptin-deficient (ob/ob) and diet-induced obesity (DIO) mice." (PMID 40141314, 2025). "In contrast to leptin, adiponectin generally has anti-tumorigenic effects, and its levels are often reduced in obesity, leading to an increased risk of gastrointestinal cancers through several mechanisms." (PMID 40722646, 2025). "Leptin is secreted predominantly by white adipose tissue, and its circulating levels correlate directly with fat mass; consequently, obesity is associated with chronically elevated leptin concentrations." (PMID 41516046, 2025). "Current pharmacological and behavioral therapies for obesity induce initial weight loss, but this effect is transient due to leptin resistance." (PMID 39897330, 2025). "This early onset susceptibility to leptin resistance influenced the propensity of the BPA‐exposed offspring to develop obesity, and they showed a significant increase in body weight starting at 7 months of age." (PMID 39792613, 2025). "Leptin resistance, mainly caused by the decrease in tissue sensitivity to the circulating leptin, results in hyperleptinemia, hyperphagia, obesity and metabolic disorders." (PMID 40066865, 2025). "In fact, adiponectin has been previously shown to be downregulated in patients with obesity and a low adiponectin to leptin (Adpn/Lep) ratio suggests an increased cardiometabolic risk, systemic inflammation and oxidative stress." (PMID 39305371, 2025). "The Lepob/ob obesity mouse model was included because it carries a mutation in the leptin gene that results in severe obesity and metabolic dysregulation." (PMID 41226599, 2025). "The leptin-melanocortin signaling pathway, in particular, has been identified as being important, as naturally occurring mutations in the leptin and leptin receptor gene explained the severe obesity of the ob/ob and db/db mice, respectively." (PMID 40702736, 2025).
Obesity (continued). "The dysregulation of adipokines, particularly leptin and adiponectin, is another mechanism of obesity leading to a risk of gastrointestinal cancer." (PMID 40722646, 2025). "Given the rarity of this type of obesity, we present the case of a patient with a specific mutation in the LEP gene reported only once and share our experience with treatment over recent years." (PMID 41013830, 2025). "These genes, involved in leptin-related neuronal pathways, are linked to obesity and metabolic disease, suggesting a depot-specific effect on neuronal outgrowth in OVAT." (PMID 40118008, 2025). "Obesity-incited decline in leptin responsiveness, known as leptin resistance, causes adipocytes to produce more leptin and results in hyperleptinemia as a way for the body to make up for the dampened leptin responsiveness." (PMID 39777720, 2025). "Obesity is also associated with shifts in the individuals’ endocrine profile, with high leptin and low adiponectin coming from the expanding adipose tissue." (PMID 40002337, 2025). "On the other hand, leptin and leptin receptor polymorphisms have been related to obesity, which has been ascribed to the relationship between body weight and eating behaviors." (PMID 40559461, 2025). "In chronic inflammation, obesity, and autoimmunity, DC-induced T cell activation is associated with increased levels of leptin." (PMID 41516046, 2025). "PA improves hypothalamic inflammatory states by reducing obesity-associated pro-inflammatory mediators (e.g., free fatty acids, TNFα, adiponectin, and advanced glycation end-products), thereby restoring leptin sensitivity and decreasing food intake." (PMID 41358225, 2025). "The most prevalent genes linked to monogenic obesity are leptin (LEP), leptin receptor (LEPR), and melanocortin 4 receptor (MC4R) genes." (PMID 40024983, 2025). "Monogenic Obesity is linked to gene mutations related to the hypothalamic leptin-melanocortin signaling pathway." (PMID 41302083, 2025). "Comprehensive endocrine evaluation, including pituitary axis profiling, dynamic growth hormone testing, and assessments of insulin and leptin resistance, excluded secondary causes of obesity and reinforced the likelihood of a monogenic etiology." (PMID 40428329, 2025). "Increased serum leptin levels are directly associated with higher adipose tissue mass and are a significant contributor to obesity and its metabolic complications." (PMID 40529825, 2025). "Research with ob/ob mice has shown that leptin-deficient obesity increases the risk of periodontitis." (PMID 41244040, 2025). "Obesity also elevates cancer risk and worsens prognosis by altering levels of insulin, insulin-like growth factor 1, leptin, adiponectin, steroid hormones, and cytokines." (PMID 40864791, 2025). "Leptin also plays a critical role in glucose homeostasis, as demonstrated in models of obesity and type 2 diabetes (T2D), such as leptin-deficient (ob/ob) and leptin receptor-deficient (db/db) mice." (PMID 41226331, 2025). "Elevated leptin levels are commonly associated with obesity and metabolic syndrome, where leptin resistance impairs its regulatory functions, contributing to further metabolic derangements." (PMID 40152811, 2025). "Fourth, adipokines such as leptin and adiponectin derived from adipose tissue play a significant role in the regulation of obesity‐associated T3 inflammation." (PMID 40329860, 2025). "Circadian misalignment in individuals with genetic predispositions to obesity disrupts the release of key metabolic hormones, such as leptin and insulin, impairing hunger regulation and fat storage." (PMID 40024983, 2025). "This multifaceted impact of leptin signaling deficiency underlines the inadequacy of classifying such conditions as strictly non-syndromic obesity." (PMID 39237720, 2025). "In obesity, overexpression of leptin increases cancer development risk, poor prognosis, and decreases the efficacy of immunotherapy against cancers." (PMID 40863244, 2025).
Obesity (continued). "Other researchers have verified that chronic JAK-STAT3-SOCS3 signaling induced by leptin and IL-6 is implicated in obesity, cancer, and aging." (PMID 40149853, 2025). "ob/ob mice, which possess a mutation in the leptin gene, resulting in obesity characterized by hyperphagia and reduced energy expenditure." (PMID 40024983, 2025). "Preclinical and clinical evidence suggests that leptin is a crucial player in obesity-associated ED and hypertension especially in females, due to the increase in the association between leptin and aldosterone." (PMID 39857433, 2025). "Obesity is associated with a range of changes in metabolic cytokines and hormones, including leptin, gastrin, insulin, and certain central lipids." (PMID 40150457, 2025). "Pathophysiological mechanisms underlying obesity include insulin resistance, leptin dysregulation, and altered gut microbiota, which perpetuate metabolic derangements." (PMID 39940332, 2025). "Contemporary classifications of obesity distinguish between hypoleptinemia, characterized by inadequate hormone production, and hyperlipidemia, which is associated with leptin resistance." (PMID 40565688, 2025). "Although leptin deficiency represents a rare monogenic cause of severe early-onset obesity, common forms of obesity are usually associated with elevated circulating leptin levels and resistance to its anorexigenic and energy expenditure-stimulating effects." (PMID 40944223, 2025). "Adipocyte-derived factors, notably adipokines such as leptin, which is typically elevated in obesity, have been linked to increased cell growth and invasion." (PMID 40386210, 2025). "This relationship was reported to be partially driven by leptin, which is associated with an increase in the efficacy of PD-1/PD-L1 blockade, emphasizing that obesity can represent a valuable biomarker for certain cancer immunotherapies." (PMID 40835772, 2025). "Underlying these rare forms of obesity are key signaling pathways, such as the leptin–melanocortin-4 receptor (MC4R) pathway, which centrally regulates energy balance and food intake through select hypothalamic structures." (PMID 39856371, 2025). "Longitudinal studies are required to gain a deeper understanding of the dynamic changes in LEP bioactivity over time and their impact on obesity progression and associated complications." (PMID 40586327, 2025). "Elevated leptin levels in the HFD group reflect typical leptin resistance associated with obesity, where increased fat accumulation enhances leptin production while decreasing leptin sensitivity." (PMID 40535914, 2025). "Patients with monogenic obesity due to homozygous LEP variants can be treated with recombinant leptin to correct the deficiency." (PMID 40560452, 2025). "Third, post-prandial satiety response is less pronounced with obesity, though fasted leptin and ghrelin are positively associated with obesity." (PMID 40458765, 2025). "Maternal metabolic health can also shape the DNA methylation profile of leptin at birth, thereby influencing the metabolic reprogramming associated with obesity." (PMID 40278960, 2025). "The ZDF rats, as a genetic model of obesity, exhibit hyperleptinemia and associated leptin resistance, which results in a deterioration in insulin sensitivity." (PMID 39576482, 2025). "PTP1B directly dephosphorylates JAK2, and PTP1B-deficient mice display reduced food intake, increased leptin sensitivity, and resistance to diet-induced obesity." (PMID 41516046, 2025). "ROC analysis indicated that leptin had the highest diagnostic accuracy for predicting obesity in PCOS (area under the curve [AUC] =0.85, 95% CI: 0.79-0.91, p<0.001)." (PMID 40792318, 2025). "Obesity, particularly abdominal obesity, is strongly associated with HS severity, as visceral adipose tissue secretes pro-inflammatory adipokines like leptin and resistin, which promote Th1 and Th17 polarization." (PMID 39858932, 2025).
Obesity (continued). "Associations between the leptin and ghrelin levels and the clinical variables related to the sarcopenic obesity parameters were examined via multivariable linear regression." (PMID 39599699, 2024). "On the other hand, the gene expressions of HSL and Leptin were significantly increased, exhibiting the most potent effect within the two TMEs (Ob-PA-T and Ob-MA-T) associated with obesity." (PMID 39072314, 2024). "Elevated leptin expression, rare mutations, and single-nucleotide polymorphisms (SNPs) have been identified in individuals with moderate and severe obesity." (PMID 39201522, 2024). "Since leptin was shown to induce autophagy in healthy peripheral tissues, the interest has grown in elucidating the role of autophagy in leptin-driven malignant features of obesity-linked cancer." (PMID 38228661, 2024). "Obesity is associated with increased leptin levels that activate the cells of the innate and adaptive immune system." (PMID 38673991, 2024). "In mammals, fat deposition is associated with leptin, which mainly promotes fat hydrolysis and inhibits fat deposition, thereby maintaining energy metabolism and preventing obesity." (PMID 39519205, 2024). "Our results confirm that overweight/obesity is associated with elevated breastmilk and serum leptin, and that these values are highly correlated." (PMID 38668349, 2024). "Hyperleptinemia, on the other hand, is a condition where leptin is produced in excess due to peripheral leptin resistance and is associated with obesity, metabolic diseases, and increased cardiovascular risk." (PMID 39335642, 2024). "Obesity and asthma have been linked through chronic systemic inflammation driven by adipokines such as leptin, adiponectin, TNF-α, monocyte chemotactic protein-1 (MCP-1), and IL-6." (PMID 40474934, 2024). "Regarding obesity and obesity-associated DM, weight loss through restrictive diets or lifestyle modifications lead to a restoration of leptin sensitivity." (PMID 38397015, 2024). "In this cohort study of patients with BC, obesity and high serum leptin levels were associated with an enhanced risk of early-onset BC and diagnosis of luminal A and TNBC subtypes in Black women." (PMID 39073818, 2024). "In order to support the obtained in vitro data, Zucker rats were used as a genetic model of obesity caused by the mutation (fa) in the gene encoding the receptor of leptin, which leads to hyperphagia and excessive adiposity." (PMID 39204091, 2024). "Despite its positive effect on hepatic LSR activity and obesity, interestingly, leptin itself is also known to cause oxidative stress." (PMID 38892018, 2024). "Cellular leptin resistance which is caused by several cellular processes that are stimulated by obesity, increases the amount of weight gain induced by environmental and genetic factors." (PMID 40259963, 2024). "This brings into focus the complex interplay between obesity and diabetes and markers such as leptin, IL6, TNFα, and IGFs in elevating the risk of endometrial cancer." (PMID 38339282, 2024). "In obesity, dysregulation of these adipokines is common, leading to leptin resistance associated with elevated leptin levels and reduced adiponectin, impairing metabolism and appetite regulation." (PMID 39771046, 2024). "Currently, eighteen mutations in the LEP gene have been identified, leading to early onset obesity [2,]." (PMID 39041042, 2024). "Leptin is a 167 amino acids peptide encoded by the obesity (ob) gene and secreted primarily by adipocytes." (PMID 38542187, 2024). "Mutations in genes implicated in the leptin–melanocortin pathway have been mostly associated with monogenic obesity." (PMID 38397265, 2024). "Overall, FO supplementation demonstrated efficacy in mitigating HFD-induced obesity, influencing epigenetic and molecular pathways, and shedding light on the role of ASCs and leptin signaling in WAT dysfunction associated with obesity." (PMID 39065712, 2024).